MMP9 (matrix metallopeptidase 9)
Diseases named in the same sentence as MMP9 in open-access papers (continued):
Sharing a sentence is not in itself a finding about the gene and the disease.
Sepsis (continued). "Compared with the sepsis group and the Sc at the corresponding time, the expression levels of NF-κB p65 mRNA, the lung injury of experimental mice, the wet/dry ratio and the levels of MMP-9 mRNA and protein activity decreased, and significant differences were observed at 6 h post-operation (P<0.05)." (PMID 24913772, 2014). "In pediatric sepsis cohorts, the combined analysis of LTF and MMP9 achieved perfect classification (the area under the curve [AUC] = 1.0) in training set GSE13904, with near-perfect validation (AUC = 0.995) in the validation set GSE80496." (PMID 41007866, 2025). "Patients with sepsis had a significantly higher expression of CTSD, GADD45A, MAPK14, MMP9, and VIM than normal health controls." (PMID 40184094, 2025). "Five hub genes including CTSD, GADD45A, MAPK14, MMP9, and VIM were upregulated in patients with sepsis compared with normal controls in the GSE28750 (peripheral blood samples) and GSE64457 (neutrophil samples) datasets." (PMID 40184094, 2025). "XBJ exerted therapeutic effects on sepsis and septic-AKI through suppression IL-1β/MMP9, IL-6/MMP9 and TNFα/MMP9 at both mRNA and protein level." (PMID 41042728, 2025). "The gene differential expression analysis showed that compared with the healthy group, the sepsis patient group exhibited significantly lower expression levels of AKT1 and BCL2, but significantly higher expression levels of MMP9, ICAM1, TLR4, and HIF1A." (PMID 41411324, 2025). "The expression levels of CTSD (P < .001), GADD45A (P < .001), MAPK14 (P < .001), MMP9 (P < .001), and VIM (P < .001) were significantly higher in patients with sepsis than in normal healthy controls." (PMID 40184094, 2025). "In our study, immunohistochemical analysis of the lung tissue of rats in the sepsis group showed significantly higher MMP-2 and MMP-9 positivity than the other 4 groups." (PMID 39860018, 2025). "Matrix metalloproteinase-9 (MMP-9) plays a role in ALI by influencing the release of sRAGE, and its knockdown exacerbates sepsis-induced ALI and inflammation by decreasing sRAGE levels." (PMID 40298887, 2025). "This study has identified 5 key genes – CTSD, GADD45A, MAPK14, MMP9, and VIM – that are significantly upregulated in sepsis patients compared to healthy controls." (PMID 40184094, 2025). "The CoIP results confirmed direct interactions between MMP8, MMP9, ARG1, and CXCL8, substantiating their roles in sepsis-related inflammatory pathways." (PMID 39560539, 2024). "This study’s bioinformatics analysis has identified significant alterations in the expression of genes such as MMP8, MMP9, and ARG1 in the granulocytes of patients with sepsis." (PMID 39560539, 2024). "Our study underscores the significant potential of biomarkers such as MMP8, MMP9, and ARG1 in advancing the early diagnosis and targeted treatment of sepsis." (PMID 39560539, 2024). "Our results showed that genes such as IFN-γ, TNF-α, IL-6, MIP-2, IL-10, KC (CXCL1), CCL-2, MPO, MMP9, TLR2, and LCN2 were significantly upregulated in the lungs of sepsis-induced ARDS mice compared to control mice." (PMID 37822934, 2023). "Our findings revealed significant decreases in CD4, CD3e, IL-7R, CD5, CD247, CD2, CD40LG, ITK, and KLRB1, and significant elevations in MMP9, LCN2, and RETN in sepsis-induced ARDS compared to controls." (PMID 37822934, 2023). "Consensus cluster analysis we successfully classified sepsis patients into two distinct groups based on the expression of 8 hub genes (IGFBP7, GMFG, IL10, IL18, ETS2, HGF, CD55, and MMP9)." (PMID 38259686, 2023). "We found that sepsis enhanced the expression of E‐cadherin, ZO‐1, MMP2, and MMP9 but weakened that of TIMP‐2 and TIMP‐3." (PMID 37525933, 2023). "In an animal model of sepsis with DVT, we found that MMP9 protein expression was significantly higher than in the control group." (PMID 38029239, 2023). "In conclusion, the present study identified core immune‐related DEGs between severe burns and sepsis, including IL10, RETN, THBS1, FGF13, LCN2 and MMP9." (PMID 37060578, 2023).
Sepsis (continued). "MMP-9 paper-based sensors fabricated and demonstrated their capability to detect the MMP-9 levels in both blood and BAL samples in sepsis-challenged mice as early as 1 h and up to 20 h post-challenge." (PMID 37622890, 2023). "Providing external validation to our findings, several genes, such as CD177, ARG1 (arginase), MMP9, OLAH and ADM have been described previously as having important inflammatory roles in sepsis." (PMID 38332914, 2023). "By leveraging bioinformatics analysis and machine learning algorithms, we systematically identified five immune-related candidate hub genes (CLEC5A, KLRB1, LCN2, MCEMP1, and MMP9) and provided a nomogram for diagnosing ROP with sepsis." (PMID 38028617, 2023). "A fecal intraperitoneal (FIP) challenge was used to induce sepsis in mice, and an MMP-9 secretion was measured by taking blood and Bronchoalveolar Lavage (BAL) fluid samples at 1 h, 2 h, 4 h, and 20 h (early sepsis) post-challenge intervals." (PMID 37622890, 2023). "While the role of MMP‐9 activity is controversial, a clinical trial showed that the active form of MMP‐9 was only present in patients with severe sepsis." (PMID 36629024, 2023). "In view of the diversity of MMP9 functions and the complexity of sepsis combined with VTE, how MMP9 is regulated and what specific functions it plays in the pathological model of sepsis combined with VTE need to be further studied in more experiments." (PMID 38029239, 2023). "Hoffmann and collaborators reported elevated levels of matrix metalloproteases and their inhibitors (MMP-9, TIMP-2 and TIMP-1) in severe sepsis, and TIMP-1 was suggested as a useful biomarker in predicting the clinical outcome of patients with severe sepsis." (PMID 37817235, 2023). "An immune cell-specific study has found that MMP9, ARG1, CXCL3, SOCS3, CCR7, and IL-10 are differentially expressed in T cells and monocytes from sepsis patients compared with healthy individuals." (PMID 35721566, 2022). "The relatively small-sized gelatinase-containing granule gene profile was dominated by increases in MMP9 and CD177 in both sepsis and SIRS." (PMID 35844509, 2022). "Not only this, but MMP‐8 levels have also been evidenced to be increased alongside MMP‐9, MMP‐2, and TIMP‐1 during early sepsis, a condition which has eventually been related to patient mortality." (PMID 35818743, 2022). "In vivo, patients with sepsis were found to have high TIMP-1 and low MMP-9 concentrations in serum, which predicted a monocyte-derived increase in TIMP-1 concentrations in peripheral blood." (PMID 36670630, 2022). "Based on degree centrality, 27 hub genes were selected, in which six genes (MMP9, CD44, EGR1, ACTN2, TNNT3, and PTGS2) were selected on the basis of a multi-network variable selection approach and validated in a well-established sepsis mice model." (PMID 35205254, 2022). "In the animal model of sepsis, MMP-2 and MMP-9 were activated, blood-brain barrier (BBB) permeability increased, and BBB permeability was reversed by MMP inhibitor." (PMID 36142454, 2022). "In conclusion, the present study revealed an unbalanced immune response at the transcriptome level of sepsis and identified genes for potential biomarkers of sepsis, such as ITK, CD247, MMP9, CD3D, MMP8, KLRK1, and GZMK." (PMID 35190763, 2022). "In abdominal sepsis, MMP-9 controls the shedding of platelet-derived CD40L, which is known to regulate neutrophil recruitment and lung damage in sepsis." (PMID 33628393, 2021). "Higher MMP-2, MMP-8, MMP-9, MMP-10, TIMP-1 and MMP-10/TIMP-1 were seen in severe sepsis compared to controls." (PMID 34043679, 2021). "Using two potential target genes (MMP9 and MPO), we established a logistic regression model aiming for pediatric sepsis prediction." (PMID 33748037, 2021). "Elevation of pulmonary MMP-9 mRNA and protein expressions was confirmed in CLP-induced mouse sepsis model." (PMID 33628393, 2021).
Sepsis (continued). "Previously, MMP-9, TIMP-1 levels, and MMP-9/TIMP-1 ratio have been suggested as biomarkers in adult severe sepsis and septic shock." (PMID 33748037, 2021). "Among the sustained upregulated genes in neutrophils post sepsis, we identified ANXA1, MMP9, SIPR1, and JUN as the candidate genes." (PMID 33761636, 2021). "Elevated levels of MMP-9 were observed in critically ill patients, and a relation of MMP-9 levels to the severity of sepsis was shown." (PMID 33488296, 2021). "The analysis of GEO mouse sepsis datasets GSE15379, GSE52474, and GSE60088 revealed that the mRNA expression of MMP-9 was significantly upregulated in septic mouse lung tissues." (PMID 33628393, 2021). "LPS induces transcription of the MMP-9 gene, and several groups have investigated the levels of MMP-9 in relation to the severity of sepsis in humans." (PMID 33488296, 2021). "Consistent with our results, it has been demonstrated that pulmonary MMP-9 is upregulated in experimental ALI animal models induced by cardiopulmonary bypass (CPB) and in patients with sepsis." (PMID 33628393, 2021). "Specifically, the expression levels of these 4 genes were increased > 4.0-fold in patients with sepsis compared with those in healthy subjects: ANXA3 (28.1-fold), S100A8 (4.9-fold), S100A9 (4.4-fold), and MMP9 (69.2-fold)." (PMID 32922168, 2020). "Thus, MMP-9 inhibition could provide a therapeutic strategy of sepsis." (PMID 31213027, 2019). "The results indicate that MMP-9, TIMP-2, and TIMP-1 showed the higher sensitivity, specificity, and positive predictive value for sepsis." (PMID 31671729, 2019). "The DEGs (IL1R2, ARG1, FCGR1A, MMP9, ELANE, and MPO) that were common on day1 and day3 of sepsis, with at least 2.0-fold upregulation, were selected for constructing and visualizing the PPI network using Cytoscape." (PMID 31817302, 2019). "This study demonstrates the role of significant and widespread immune activation (IL1R2, MMP9), along with oxidative stress (ARG1) and the recruitment of neutrophils, in sepsis (ELANE, MPO)." (PMID 31817302, 2019). "Two important mediators of an inflammatory response in sepsis, MMP-2 and MMP-9 were determined in a dose-dependent manner." (PMID 30142934, 2018). "Patients with sepsis had higher TIMP-1 levels and lower MMP-9/TIMP-1 ratios than both control groups at all time points." (PMID 29861795, 2018). "On the other hand, elevated MMP-9 and TIMP-1 expression was found in kidneys and livers of animal models of sepsis." (PMID 29861795, 2018). "We found that the inflammation indicators, NF-κB, MMP-9, RANTES, and TNF-α, along with oxidative stress and mitochondrial damage, were upregulated by ARDS with sepsis in animals." (PMID 29137274, 2017). "Compared to the NC group, protein concentrations of CXCL-12, MMP-9, VEGF, TNF-α, and NO were significantly higher in the sepsis groups." (PMID 28513569, 2017). "The MMP9/TIMP1 cut-point of < 0.36 yielded a sensitivity of 95% and specificity of 70% to diagnose sepsis." (PMID 27089280, 2016). "The principal findings of this pilot study are the potential for MMP-9/TIMP-1 ratios, A-FaBP and mrProANP levels to serve as biomarkers for the identification of sepsis in pediatric patients." (PMID 27089280, 2016). "In two studies, plasma levels of both MMP-9 and TIMP-1 were significantly higher in patients with severe sepsis compared with healthy controls on day 1 of severe sepsis." (PMID 27089280, 2016). "In that study, the blister fluid in the early stage of sepsis had higher MMP-8 and lower MMP-9 than in controls." (PMID 25945788, 2015). "In retrospective studies on sepsis, levels of MMP-8, MMP-9, and tissue inhibitor of metalloproteinase-1 (TIMP-1) differed from those of healthy controls, and TIMP-1 showed an association with outcome." (PMID 25945788, 2015). "The strengths of our study were the large sample size and the follow-up of circulating TIMP-1, MMP-9, TNF-alpha, IL-10, and PAI-1 levels throughout the first week after diagnosis of severe sepsis." (PMID 24727739, 2014).
Sepsis (continued). "Elevated levels of MMP-9 and TIMP-1 were reported in septic patients, and higher TIMP-1 levels at the beginning of severe sepsis were predictive of death." (PMID 25407832, 2014). "In the present study, MMP-9 was higher with increased severity of sepsis in the groups with SIRS, sepsis and severe sepsis (P <0.01), but the level decreased according to severity of septic shock." (PMID 25407832, 2014). "Compared with the healthy control group, NGAL, MMP-9 and TIMP-1 levels were significantly higher in patients with SIRS, sepsis, severe sepsis and septic shock (P <0.01)." (PMID 25407832, 2014). "In severe sepsis, from intact skin suction blister and serum samples, MMP-2 and MMP-8 levels are elevated, whereas MMP-9 is suppressed." (PMID 20356362, 2010). "Sepsis patients had higher levels of MMP-10 and TIMP-1, higher MMP-10/TIMP-1 ratios, and lower MMP-9/TIMP-1 ratios than did healthy controls (P < 0.001)." (PMID 19799791, 2009). "The objective of this study was to determine the predictive value of MMP-9, MMP-10, and TIMP-1 on clinical severity and mortality in a large series of patients with severe sepsis." (PMID 19799791, 2009). "Serum levels of MMP-9, MMP-10, TIMP-1, tumor necrosis factor (TNF)-alpha, and interleukin (IL)-10 were measured in patients with severe sepsis at the time of diagnosis and in healthy controls." (PMID 19799791, 2009). "Previous studies with small sample sizes (fewer than 40 patients) have shown higher levels of MMP-9 and TIMP-1 in sepsis patients than in controls." (PMID 19799791, 2009). "Additionally, THCQ has been found to regulate critical target genes in sepsis patients (such as MAPK14, MAPK3, MMP9, STAT3, and LYN), which play key roles in cellular inflammatory responses, especially through the modulation of the MAPK and Nrf2 pathways." (PMID 40963685, 2025). "Mechanistically, we demonstrate that MMP9 suppresses NFAT activation by impairing TCR signaling via Lair-1-mediated ZAP70 inhibition and by disrupting CRAC-channel-dependent calcium influx—interactions previously unrecognized in the context of sepsis." (PMID 41306770, 2025). "Marker of fibrosis Mmp9 was increased upon sepsis (P < 0.001), but not Ctgf, and neither were further affected by rAAV-sh treatment." (PMID 41385533, 2025). "Earlier studies have shown that plasma MMP-9 concentrations may be a useful prognostic marker in septic shock, TIMP-1/MMP-9 ratio is correlated with sepsis severity and coagulation index, and may be a new biomarker of sepsis outcome." (PMID 38029239, 2023). "The expression of MMP-9 in platelets increases during septic shock, suggesting that MMP-9 could be a potential therapeutic target for thrombocytopenia in sepsis." (PMID 37841241, 2023). "CD177, ARG1, FAM20A, PCOLCE2, SLC51A, MMP9, were identified as most significantly upregulated in both SIRS and Sepsis on Day1, compared with healthy controls, with CD177 and ARG1 consistently higher for both SIRS and Sepsis at this and across all timepoints to discharge." (PMID 38332914, 2023). "The activation of MMP-2 and MMP-9 by LPS induces the release of TNF-α, which can raise MMP-2 and MMP-9 levels in the blood of patients with sepsis in response to a Gram-negative bacterial infection." (PMID 37504075, 2023). "However, only three genes (CD44, MMP9, and EGR1) were found to be significantly upregulated in the sepsis model, correlating with our bioinformatic results." (PMID 35205254, 2022). "In addition, administration of sRAGE suppressed the activation of the RAGE signaling pathway and attenuated ALI induced by intrapulmonary knockdown of MMP-9 and CLP-induced sepsis." (PMID 33628393, 2021). "For example, inhibition of MMP-9 attenuates neutrophilic inflammation and pulmonary injury in ventilator-induced lung injury model and improves survival in rodent models of cecal ligation and puncture- (CLP-) induced sepsis." (PMID 33628393, 2021).
Sepsis (continued). "In the group negative for sepsis, MMP-9 concentrations were 107.8 (75.8–134.3) ng/ml in plasma and 51.9 (18.9–74.8) ng/ml in PF, respectively." (PMID 33488296, 2021). "Lorente and coworkers found a significant increase of TIMP-1, and nonsignificantly higher MMP-9 levels, in sepsis patients, and both proteins were significantly higher in nonsurvivors." (PMID 32258173, 2020). "There are several reports demonstrating an increase in MMP-9 and TIMP-1 levels in sepsis." (PMID 32190734, 2020). "MMP-9, TIMP-1, biomarkers of inflammation, kidney and liver injury, coagulation, and metabolic disorders were measured daily during 96 h following diagnosis of sepsis and once in controls." (PMID 29861795, 2018). "TIMP-1, unlike MMP-9 and MMP-9/TIMP-1 ratio, was a good diagnostic and prognostic biomarker of sepsis after major abdominal surgery." (PMID 29861795, 2018). "Our results show an increase in the MMP9 activity without a change in the MMP2 activity in the animals' liver of the sepsis group." (PMID 30524657, 2018). "AUC-ROC for diagnosis of sepsis was 0.940 and 0.854 for TIMP-1 and 0.924 and 0.788 for MMP-9/TIMP-1 ratio (sepsis versus nonoperated and sepsis versus operated controls, resp)." (PMID 29861795, 2018). "TIMP-1 and MMP-9/TIMP ratio were, unlike MMP-9, very good discriminators between patients with sepsis and both control groups at all time points." (PMID 29861795, 2018). "A reduction in MMP-9/TIMP-1 ratio (Median, IQR, n) has been reported in adults with sepsis." (PMID 27089280, 2016). "Previous studies in adults measuring MMP-9 and TIMP-1 in sepsis have shown variable results." (PMID 27089280, 2016). "MMP-9 levels (Median, IQR ng/mL, n) for the sepsis group on day 1 (5.3, 1.8–38.7, 13), day 2 (12.4, 0.7–15.7, 11), and day 3 (6.4, 0.9–16.9, 22) were lower than febrile (61, 24.7–90.9, 28) and healthy controls (41.8, 27.4–76.0, 29); (p< 0.05 for days 1, 2, and 3)." (PMID 27089280, 2016). "Moreover, compstatin counteracted the effects of E. coli sepsis on the expression of matrix metalloproteinases MMP8, MMP9 and MMP14." (PMID 26337158, 2015). "Matrix metalloproteinase-9 (MMP-9) and its inhibitor, tissue inhibitor of matrix metalloproteinase-1 (TIMP-1), are promising novel biomarkers to predict the severity and outcome of sepsis, and are involved in the pathogenesis of sepsis and septic shock." (PMID 25407832, 2014). "In addition, NGAL, MMP-9, TIMP-1 levels and MEDS score were significantly higher in sepsis, severe sepsis and septic shock than in SIRS (P <0.01)." (PMID 25407832, 2014). "Active forms of MMP-2 and MMP-9 are only found in some patients with severe sepsis, but not in controls." (PMID 20356362, 2010). "In the largest of previous patient samples MMP-9 was not significantly higher in sepsis patients and a negative correlation was found to organ failure parameters." (PMID 20356362, 2010). "After analyzing MMPs and TIMP-1 levels in relation to mortality, in our study, we found higher plasma levels of TIMP-1 and lower levels of MMP-9 in nonsurviving sepsis patients." (PMID 19799791, 2009). "Thus, the objective of this study was to determine the influence of the circulating levels of MMP-9, MMP-10, and TIMP-1 on the severity and mortality of patients with sepsis in a large cohort." (PMID 19799791, 2009). "• MMP-9/TIMP-1 ratio and MMP-10 levels may be of great pathophysiologic significance in terms of severity and mortality in sepsis patients." (PMID 19799791, 2009). "Taken together, these results indicate that an alteration in the MMP-9/TIMP-1 ratio and MMP-10 levels may be of great pathophysiologic significance in sepsis patients." (PMID 19799791, 2009). "Nonsurviving sepsis patients had lower levels of MMP-9 (P = 0.037), higher levels of TIMP-1 (P < 0.001), lower MMP-9/TIMP-1 ratio (P = 0.003), higher levels of IL-10 (P < 0.001), and lower TNF-α/IL-10 ratio than did surviving patients." (PMID 19799791, 2009).